NLRP3 (NLR family pyrin domain containing 3)
Diseases named in the same sentence as NLRP3 in open-access papers (continued):
Sharing a sentence is not in itself a finding about the gene and the disease.
Cognitive impairment (continued). "IAA has been recently reported to penetrate the blood–brain barrier and alleviate cognitive impairment and AD‐like pathology by suppressing Nlrp3 transcription." (PMID 40219707, 2025). "The present study confirmed that W. coagulans BC99 ameliorated cognitive impairment in chronic sleep-deprived mice by improving gut microbiota, especially by promoting SCFAs production and inhibiting the NLRP3 signaling pathway in the jejunum and brain." (PMID 40232008, 2025). "NLRP3 inflammatory vesicles were identified as a key component of the observed cognitive impairment reversed by W. coagulans BC99 administration in mice." (PMID 40232008, 2025). "HFD feeding significantly exacerbated Tau pathology and NLRP3 inflammasome activation in 3xTg‐AD mice, leading to pronounced cognitive deficits." (PMID 40589337, 2025). "Astrocyte-specific NLRP3 knockout reversed surgery-induced impulsivity and cognitive deficits in aged mice." (PMID 40914484, 2025). "This confirms the therapeutic potential of NLRP3-mediated pyroptosis in TBI and prompts multiple interventions targeting NLRP3 to alleviate post-TBI cognitive impairment." (PMID 41369366, 2025). "Our findings further demonstrated that TXNIP overexpression contributed to neuronal injury by activating the ERS/NLRP3 inflammasome pathway, leading to cognitive impairments in DCD." (PMID 39629879, 2025). "These molecules reduce NLRP3-inflammasome activation and IL-1β levels in the brain, rescuing cognitive impairment in AD models." (PMID 41280719, 2025). "The association between NLRP3 expression and cognitive impairment, as measured by GDS, further supports NLRP3’s role in HIV-associated NCI." (PMID 41280902, 2025). "Specifically, chronic sleep loss induces intestinal dysbiosis and promotes activation of the NOD-like receptor family pyrin domain-containing 3 (NLRP3) inflammasome within both colonic and cerebral tissues, ultimately contributing to cognitive deficits." (PMID 41458114, 2025). "Collectively, blocking Tau‐induced NLRP3 acetylation to inhibit inflammasome activation by TNB peptide rescues cognitive impairment in Tau‐overexpressing mice." (PMID 38488468, 2024). "Previous studies have demonstrated that the pyroptosis and neuroinflammation mediated by the P2 × 7R/NLRP3 signaling pathway can lead to cognitive impairment in a mouse model of migraine." (PMID 38573415, 2024). "RAGE binds directly to RIPK1 via the amino acid sequence (AAs) 362–367, thereby upregulating phosphorylation of RIPK1, which results in activation of the NLRP3 inflammasome in microglia and ultimately leads to cognitive impairments in db/db mice." (PMID 37665158, 2024). "Inhibiting ER stress alleviated cognitive impairment in A/S mice; particularly, ER stress induced by A/S results in NLRP3 inflammasome activation and neuroinflammation." (PMID 39432407, 2024). "Limited binding of HMGB1 and MD-2 downregulates the expression of NLRP3, thereby alleviating neuroinflammation and cognitive impairment in CLP model mice." (PMID 38734709, 2024). "Lastly, competitive binding of TNB peptide to Tau protein inhibited its acetylation effect on NLRP3 and downstream inflammasome activation in microglia, thereby alleviating cognitive impairment." (PMID 38488468, 2024). "The NLRP3/Caspase-1 pathway-induced pyrodeath can result in cognitive impairment in SAE mouse models." (PMID 39027435, 2024). "• Competitive binding of a designed TNB peptide to block the interaction of Tau with NLRP3 inhibits the NLRP3 acetylation and downstream inflammasome activation in microglia, thereby alleviating cognitive impairment in mice." (PMID 38488468, 2024). "Recent studies show that IS is a significant uremic toxin inducing NLRP3 inflammasome-mediated cognitive impairment in microglia and astrocytic inflammation." (PMID 39595807, 2024).
Cognitive impairment (continued). "In vivo, TNB peptide blocked Tau‐induced NLRP3 acetylation to inhibit inflammasome activation and microglia activation and then rescued cognitive impairment in Tau‐overexpressing mice." (PMID 38488468, 2024). "In different CNS diseases, inhibition of NLRP3 inflammasome signaling has been reported to regulate neuroinflammation and result in the development of long‐term cognitive impairment, including ischemic stroke." (PMID 38421089, 2024). "In sleep deprivation-induced cognitive impairment, chronic sleep deprivation induces gut dysbiosis in mice, activating NLRP3 inflammasomes in the colon and brain." (PMID 38801630, 2024). "Animal experiments have shown that mice in the A/S group exhibited cognitive impairments accompanied by increased Hspa5 and Xbp1 expression, ER stress, and activation of NLRP3 inflammasome." (PMID 39432407, 2024). "Isoflurane induces hippocampal inflammatory responses and cognitive deficits through activation of the NLRP3/caspase-1 axis." (PMID 37962460, 2024). "Histone deacetylases inhibitor also improved cognitive impairment, up-regulated histone acetylation levels, ameliorated autophagy impairments and suppressed the activation of NLRP3 inflammasome in the hippocampus from sevoflurane-stimulated aged mice." (PMID 37548945, 2024). "Specific inhibition of NLRP3 in vivo attenuated the activity of NLRP3 producing promising results, such as the decreased levels of tau and Aβ aggregates and the reduced cognitive impairment." (PMID 38275516, 2024). "Anesthesia and surgery‐induced upregulation of Hspa5 and Xbp1 gene expression subsequently led to ER stress, NLRP3 inflammasome activation, and neuroinflammation, potentially contributing to cognitive deficits in aged mice." (PMID 39432407, 2024). "Induced neuronal damage and cognitive impairment by activation of NF-κB pathway and NLRP3 inflammasome." (PMID 37962460, 2024). "Overall, our results suggested that mitophagy was related in NLRP3 inflammasome-induced cognitive deficits after anesthesia and surgery in aged mice." (PMID 38145993, 2024). "Administering glycyrrhizin, an HMGB1 blocker, successfully prevented cognitive deficits and inhibited NLRP3/ASC inflammasome and microglial activation in rat offspring." (PMID 39093513, 2024). "First, we did not identify specific mechanism by which mitophagy inhibited NLRP3 inflammasome activation in anesthesia/surgery-induced cognitive impairment." (PMID 38145993, 2024). "• Tau overexpression in mouse hippocampal CA1 neurons induces cognitive impairment, Tau transmission to microglia and microgliosis with NLRP3 acetylation and inflammasome activation." (PMID 38488468, 2024). "Specifically, MINO effectively rectified the LPS-induced cognitive impairment by effectively suppressing the NLRP3/caspase-1 signaling." (PMID 38329438, 2024). "Studies have shown that targeting the NLRP3 inflammasome signaling pathway in microglia effectively attenuates cognitive deficits in PND and is a potential target for the prevention and treatment of neuroinflammatory diseases." (PMID 37962460, 2024). "TRPM2 exacerbates neuroinflammation and cognitive deficits through its role in NLRP3 inflammasome activation." (PMID 39411285, 2024). "In conclusion, our findings suggest that ER stress‐induced activation of the NLRP3 inflammasome mediates neuroinflammation and cognitive deficits following A/S, which can be effectively reversed by the administration of an ER stress inhibitor." (PMID 39432407, 2024). "In this study, we demonstrate that HSV-1 infection leads to Aβ deposition, activation of NLRP3 inflammasome, and accelerated cognitive deficits in 5xFAD mice." (PMID 39026249, 2024). "Inflammatory responses mediated by the NLRP3 inflammasome contribute to motor and cognitive impairments following TBI." (PMID 37702890, 2024). "NLRP3 is a key molecule involved in inflammasome activation, and knocking out NLRP3 can reverse cognitive impairments in APP/PS1 mice." (PMID 39232848, 2024).
Cognitive impairment (continued). "Direct binding of RAGE AAs 362–367 to RIPK1 is responsible for activation of RIPK1 and the NLRP3 inflammasome, leading to subsequent cognitive deficits." (PMID 37665158, 2024). "In a mouse model of a stroke, the upregulation of mitophagy ameliorated cognitive deficits by inhibiting NLRP3 inflammasome activation." (PMID 38786094, 2024). "Lastly, competitive binding of Tau–NLRP3‐binding blocking (TNB) peptide to Tau protein inhibited its acetylation effect on NLRP3 and downstream inflammasome activation in microglia, thereby alleviating cognitive impairment in model mice." (PMID 38488468, 2024). "Oral administration of OLT1177, an NLRP3 inhibitor reduces microglial activation and improves cognitive deficits in APP/PS1 mice." (PMID 38659577, 2024). "Our data suggest that JNK‐IN‐8 treatment improves ARDS‐induced cognitive impairment by inhibiting the JNK/NF‐?B‐mediated NLRP3 inflammasome." (PMID 36987783, 2023). "In this study, we explored the potential role of the Hsp22/NLRP3/Caspase-1/IL-1β axis in LPS-induced hippocampal neuroinflammation and cognitive impairment in mice." (PMID 36934348, 2023). "Acupuncture can also ameliorate cognitive impairment in stroke rats by modulating melatonin‐mediated autophagy and inhibiting NLRP3 inflammasome activation." (PMID 37088947, 2023). "The activation of the NLRP3 inflammasome in microglia induces the conversion of A1 astrocytes, thereby exacerbating a decline in neo-neurons and leading to cognitive impairment following exposure to LPS." (PMID 37891821, 2023). "Dexmetomidine alleviates hippocampal damage and cognitive impairment caused by liver ischemia/reperfusion in young rats by activating SIRT3-mediated mitophagy and inhibiting the activation of NLRP3 inflammasomes." (PMID 38012584, 2023). "Microglia and astrocytes, which function as effectors of neuroinflammation, exacerbate cognitive impairment via the NLRP3 inflammasome, mediating inflammation and neuronal cell death." (PMID 37915104, 2023). "It has been determined that the NLRP3/caspase-1 pathway plays a crucial role in isoflurane-induced cognitive impairment." (PMID 37179548, 2023). "In summary, the results show that the activation of the NLRP3/Caspase-1/IL-1β signaling pathway negatively regulates the hippocampal neuroinflammation and cognitive impairment induced by LPS." (PMID 36934348, 2023). "Our results revealed that CY-09 inhibited NLRP3 and its downstream activation and thus reduced inflammation and cognitive impairment." (PMID 37179548, 2023). "The results exhibited that inhibition of the NLRP3 inflammasome by CY-09 helped to relieve the cognitive impairment of the 3×Tg-AD mice." (PMID 36978970, 2023). "As expected, aged APP/PS1 mice exhibited severe deficits in spatial memory whereas APP/PS1/NLRP3-/- mice were protected from this cognitive impairment." (PMID 37509487, 2023). "This interleukin is a downstream effector of the activated NLRP3 inflammasome, and Nlrp3 knockout mice treated with LPS were protected from cognitive impairment." (PMID 36915214, 2023). "Conversely, pretreatment with Bay-11-7082, a selective inhibitor of the NLRP3 inflammasome and an NF-κB inhibitor, decreased neuronal damage and cognitive impairment, which is related to NF-κB/NLRP3 inflammasome activity." (PMID 37450925, 2023). "Inhibiting the NLRP3 inflammasome in activated microglia has produced beneficial reduction in cognitive deficits." (PMID 36776829, 2023). "Considering the crucial role of NLRP3 inflammasomes in cognitive impairment, our study revealed a correlation between the NLRP3 inflammasome and cognitive impairment following IH." (PMID 37312196, 2023). "Our data suggest that JNK‐IN‐8 treatment improves ARDS‐induced cognitive impairment by inhibiting the JNK/nuclear factor‐κB‐mediated NLRP3 inflammasome." (PMID 36987783, 2023).
Cognitive impairment (continued). "It is necessary to clarify the potential mechanism of Hsp22 in neuroinflammation-mediated cognitive impairment and the role of Hsp22 in regulating the activation of the NLRP3/Caspase-1/IL-1β pathway." (PMID 36934348, 2023). "First, we showed that in response to CCH, hippocampal neurons underwent NLRP3 inflammasome-mediated pyroptosis, leading to neuronal damage, synaptic dysfunction and ultimately cognitive impairment." (PMID 37932279, 2023). "Increased miR-146a-5p levels in microglia improved NLRP3 inflammasome and inflammatory factors by targeting the regulation of HIF1α/mtROS pathway, and inhibition of NLRP3 inflammasome alleviated cognitive impairment of mice exposed to IH." (PMID 37312196, 2023). "Baicalin alleviates cognitive impairment and protects neurons from microglia-mediated neuroinflammation via inhibiting NLRP3 inflammasomes and the TLR4/NF-κB signaling pathway." (PMID 36838564, 2023). "Studies have shown that cognitive impairment is often accompanied by inflammation and microglial activation, and that excessive activation of NLRP3 greatly aggravates the pathological process of cognitive impairment." (PMID 37915104, 2023). "Targeting and downregulation of the pyroptosis signaling pathway was an effective method to improve cognitive impairment, NLRP3 inhibitor and caspase-1 inhibitor were the most common agents to repress the activation of pyroptosis." (PMID 37332874, 2023). "Manual acupuncture (MA) at ST36 and GV20 suppresses OS and inflammation by reducing TXNIP-mediated upregulation of hippocampal NLRP3 and IL-1β, thereby reducing cognitive impairment and neuronal death in VD rats." (PMID 36925735, 2023). "We also explore the intrinsic relationship between the NLRP3 inflammasome and cognitive impairment, which involves immune cell activation, cell apoptosis, oxidative stress, mitochondrial autophagy, and neuroinflammation." (PMID 37915104, 2023). "Taken together, these data suggest that astrocyte-specific NLRP3 knockout ameliorates impulsive-like behaviors and cognitive impairment post-surgery." (PMID 37434240, 2023). "In present work, we provided evidence that NLRP3 inflammasomes was involved in postoperative cognitive impairment." (PMID 36696410, 2023). "Together, these data suggest that JNK‐IN‐8 improves ARDS‐induced cognitive impairment by mediating NLRP3 inflammasome activation." (PMID 36987783, 2023). "Meanwhile, EA exerts neuroprotective effects and ameliorates cognitive impairment by regulating mitochondrial autophagy-related proteins through melatonin and inhibiting reactive oxygen species induced NLRP3 inflammasome activation." (PMID 37735698, 2023). "A study showed that systemic inflammation downregulates amyloid-β clearance and affects microglial morphology in an NLRP3-dependent manner, ultimately leading to cognitive impairment." (PMID 38125810, 2023). "It has been postulated that the NLRP3 inflammasome promotes cognitive impairment by triggering the inflammatory response in the brain." (PMID 37450925, 2023). "We found that JNK inhibitor 8 (JNK‐IN‐8) alleviated cognitive impairment, neuroinflammation, and NLRP3 inflammasome activation in the ARDS rat model." (PMID 36987783, 2023). "Further, researches on the role of NLRP3 inflammasome in cognitive deficits is growing, although more studies have been conducted on microglia." (PMID 37312196, 2023). "Inhibition of NLRP3 inflammasome activation helps to reduce Aβ deposition and improve cognitive impairment." (PMID 36978970, 2023). "Recent studies have shown that cognitive impairment can be reversed by inhibiting the NLRP3–caspase-1 pathway." (PMID 37915104, 2023). "This study helps to further improves our understanding of the molecular mechanism of NLRP3 activation, and provides potential new therapeutic targets for the treatment of cognitive impairment." (PMID 36934348, 2023).
Cognitive impairment (continued). "The application of NLRP3 inflammasome inhibitors or RNA knockdown technology (siRNA-NLRP3) in cognitive impairment models can restore the expression of inflammasomes to normal and significantly improve cognitive function." (PMID 37165444, 2023). "In another study, treatment with ethyl pyruvate significantly reduced cognitive impairment in CLP mice by inhibiting NLRP3 and inducing IL-1β cleavage." (PMID 35958583, 2022). "Other inhibitors of NLRP3 inflammasome also exhibited neuroprotective effects, with the ability to improve neuronal damage and cognitive impairment, including Bay 11–7082 and VX-765." (PMID 36160384, 2022). "Here, we showed that liver-derived ApoE4 triggers cognitive impairments, motor and depressive- or anxiety-like behaviours by activating NLRP3 inflammasome." (PMID 35468877, 2022). "We confirmed that the surgery induced cognitive impairment and increased the levels of pro-inflammatory cytokines by activating the NLRP3 inflammasome." (PMID 35955939, 2022). "NU9056 can reduce LPS-induced cognitive impairment and affective disorders in mice by inhibiting NLRP3 inflammasome activation." (PMID 35722622, 2022). "The present study is aimed at exploring the effects of P2X4/NLRP3 signaling pathway in neuroinflammation and cognitive impairment after surgery." (PMID 35153623, 2022). "Together, this study suggested that DNLA attenuated NLRP3-mediated pyroptosis to generate neuroprotection against LPS-induced neuronal damage and cognitive impairment." (PMID 35586062, 2022). "Evidence has shown that quercetin improves cognitive impairment in aging mice by suppression of nod-like receptor protein 3 (NLRP3) inflammasome activation." (PMID 36032542, 2022). "In contrast, the NLRP3 inhibitor MCC950 (a specific small-molecule inhibitor of the NLRP3 inflammasome) was found to ameliorate isoflurane-induced pyroptosis while improving cognitive impairment." (PMID 35722622, 2022). "Hyperactivated NLRP3 inflammasome and IL-1β-mediated inflammatory responses in microglia are involved in hypoxemia and isoflurane-induced cognitive impairment in adult rats." (PMID 36456961, 2022). "moreover, quercetin was found to improve cognitive disorder in aging mice by inhibiting NLRP3 inflammasome activation." (PMID 36483000, 2022). "ROS cause rapid processing by NLRP3 inflammasomes and secretion of IL-1β, which is increased in the CNS of PWH with cognitive impairment." (PMID 35740279, 2022). "Isoliquiritigenin, a phenolic compound obtained from licorice, was shown to heal cognitive impairment and early brain injury by blocking NLRP3 inflammasome through Nr2 upregulation." (PMID 35418995, 2022). "As known, NLRP3 inflammasome can be activated by Aβ, leading to IL-1β overproduction, neuroinflammation, and cognitive impairment." (PMID 34209586, 2021). "In this study, the effect of DEX on surgery-induced inflammation and cognitive impairment by minimizing NLRP3 activation was confirmed in mice and cellular models." (PMID 34079457, 2021). "Very recently, Chikusetsu saponin IVa was used to alleviate SEVO-induced neuroinflammation and cognitive impairment by blocking NLRP3, likely through reducing apoptosis of neuronal cells." (PMID 34924922, 2021). "In vivo experiment, isoflurane induced microglial inflammation and cognitive impairment in aged mice through the NLRP3-Caspase-1 pathway." (PMID 34497527, 2021). "In this study, both the HMGB1 inhibitor and the NLRP3 knockout markedly alleviated cognitive deficits." (PMID 34539383, 2021). "In particular, the NLRP3 inflammasome, which is involved in both infectious and sterile inflammation, has recently been considered a potential therapeutic target for cognitive impairments such as AD." (PMID 34539383, 2021).